WWOX (WW domain containing oxidoreductase)
Diseases named in the same sentence as WWOX in open-access papers (continued):
Sharing a sentence is not in itself a finding about the gene and the disease.
lung carcinoma (29 papers, 2009 to 2026). "Recently, the deletion of WWOX exon 6–8 was identified in lung cancer, resulting in a loss of the tumor suppressor function." (PMID 28426730, 2017). "Evidence of individuals with low Wwox-protein levels, being more predisposed to the development of lung cancer and gliomas, also supports a role for WWOX in tumorigenesis." (PMID 28045433, 2017). "Similar studies also showed that the polymorphisms and haplotypes of WWOX gene are associated with the risk of lung cancer in southern and eastern Chinese populations." (PMID 27234396, 2013). "While WWOX loss is reported in breast, prostate, and lung cancers, its unchanged protein expression here suggests that other pathways may dominate tumorigenesis in ES." (PMID 41141138, 2025). "In this study, we hypothesized that the heterozygous WWOX exons 6–8 deletion observed in maternal grandfather (I-3, lung cancer affected individual) caused an abnormal WWOX expression and the consequent clinical phenotype." (PMID 37974179, 2023). "To differentiate the consequences of reduced gene expression of specific CFS-encoded genes, we repeated our lung cancer analysis, focusing on another tumor suppressor gene product, WWOX, expression of which is highly reduced in a large fraction of lung cancers." (PMID 25401976, 2015). "Alterations in WWOX genes are associated with lung cancer development." (PMID 27234396, 2013). "Several studies have suggested that WWOX polymorphic variants are consistently associated with more aggressive phenotypes and poor outcomes in numerous malignant diseases, including esophageal squamous cell carcinoma, thyroid carcinoma, pancreatic cancer, and lung cancer." (PMID 28426730, 2017). "However, several studies have reported a loss or downregulation of the WWOX protein and homozygous deletion within the WWOX locus in multiple malignant neoplasms such as lung cancer, pancreatic adenocarcinoma, oral cancer, ovarian cancer, and renal cell carcinoma." (PMID 27655721, 2016). "Previous studies have showed that dysregulation of WW domain-containing oxidoreductase (WWOX) participates in the generation of several cancer types, including lung cancer." (PMID 34948746, 2021). "Zheng’s study strongly suggests that WWOX inhibits invasion of lung cancer cells by inhibiting RUNX2 expression." (PMID 33946771, 2021). "Recently, two studies had reported that one germline CNV-67048 that is located in a tumor suppressor gene WW domain-containing oxidoreductase (WWOX) contributed increased risks of lung cancer and gliomas in the Chinese." (PMID 27190995, 2016). "Taken together, functional antagonism between WWOX and NF-kB is likely to occur during lung cancer initiation and progression." (PMID 27234396, 2013). "While WWOX is frequently lost in lung cancer and many other cancers, NF-κB activation-induced cancer promotion probably requires WWOX-independent signaling networks to induce expression of pro-survival factors." (PMID 27234396, 2013).
lung carcinoma (continued). "The WWOX mRNA level is downregulated in tumor tissues by hypermethylation deletion and destabilizing mutations, or it would inhibit RUNX2, reducing the invasiveness of lung cancer cells." (PMID 36551878, 2022). "The reduction or absence of WWOX expression has been found to be associated with several cancers, such as breast cancers, thyroid cancer, oral cancer, lung cancer, and so on." (PMID 34948746, 2021). "Interestingly, several reports have documented altered WWOX expression in lung cancer and lymphomas suggesting WWOX as a potential tumor suppressor in these malignancies." (PMID 30370248, 2018). "The antagonistic role of WWOX and NF-κB in the regulation of lung cancer progression is discussed." (PMID 27234396, 2013). "WWOX suppresses the expression of RUNX2 and thereby blocks the invasion and metastasis of osteosarcoma and lung cancer cells." (PMID 31315632, 2019). "miR-939 regulates a large number of genes, such as WNT1, NTSR1, POLK, WWOX and SPN, that are related to lung cancer." (PMID 29228624, 2017). "Ectopic expression of the miR-29 family in lung cancer cells restores expression of methylation-silenced tumor suppressor genes, including fragile histidine triad (FHIT) and WW domain containing oxidoreductase (WWOX)." (PMID 24348513, 2013). "MiR-29 family reverts abnormal methylation in lung cancer by targeting DNA methyltransferases 3A and 3B (DNMT3A and DNMT3B), induces re-expression of methylation-silenced tumor suppressor genes, such as FHIT and WWOX, and inhibits tumorigenicity in vitro and in vivo." (PMID 34299277, 2021).
Alzheimer disease (24 papers, 2009 to 2025). A progressive, neurodegenerative disease characterized by loss of function and death of nerve cells in several areas of the brain leading to loss of cognitive function such as memory and language. "It was observed that the loss of function of the WWOX protein was related to Alzheimer's disease, temporal lobe epilepsy, cognitive impairment, and neuropsychiatric disorders such as autism spectrum disorder." (PMID 38161429, 2023). "Mutations in WWOX have recently been found to be a significant risk factor for disease development in Alzheimer’s disease, an adult-onset neurodegenerative disorder." (PMID 33916893, 2021). "WW domain-containing oxidoreductase (WWOX) is known as one of the risk factors for Alzheimer’s disease (AD), a neurodegenerative disease." (PMID 34359949, 2021). "WWOX is a known tumor suppressor and is a risk factor for Alzheimer’s disease." (PMID 40507943, 2025). "A critical structural or functional role for the WWOX gene in the CNS would account for the observation that mutations at that locus are associated with neurodevelopmental and neurodegenerative disorders, including Alzheimer disease." (PMID 35460704, 2022). "The growing enrichment of the scientific literature about the WWOX pathogenic variant has delineated a broad impairment in neurological disorders such as Alzheimer’s disease, multiple sclerosis, autism spectrum disorders, spinocerebellar ataxia, and epileptic encephalopathy." (PMID 35573960, 2022). "Most recently, WWOX gene is determined to be a risk factor for Alzheimer′s disease (AD)." (PMID 31752354, 2019). "WWOX gene has recently been determined as a risk factor for Alzheimer’s disease." (PMID 31315632, 2019). "It has also been demonstrated that WWOX physically interacts with TPC6AΔ, an aggregated vesicle-trafficking protein isoform that has a critical role in causing caspase activation, tau aggregation, and Aβ generation in patients with Alzheimer’s disease, blocking its self-aggregation." (PMID 33916893, 2021). "The crosstalk in signaling between C1q and HA involves ERK and WWOX, suggesting that both proteins, when they become aberrant, are needed for the progression of Alzheimer’s disease." (PMID 40507943, 2025). "We will discuss how transforming growth factor beta (TGF-β1) and hyaluronan activate WWOX and downstream normal or aberrant protein partners and the potential consequences for the progression of cancer and Alzheimer’s disease (AD)." (PMID 35883580, 2022). "WWOX protein expression is significantly downregulated in the hippocampal neurons of patients with Alzheimer’s disease." (PMID 32000863, 2020). "Downregulation of WWOX protein expression has been observed in the hippocampal neurons in patients with Alzheimer’s disease." (PMID 32000863, 2020). "Switching from Y33 to S14 phosphorylation in WWOX enhances disease progression in vivo, including cancer and Alzheimer′s disease." (PMID 31752354, 2019). "The level of WWOX protein is much lower in the hippocampal neurons of those suffering from Alzheimer’s disease in comparison to healthy individuals." (PMID 31543760, 2019). "Furthermore, WWOX interacted with another protein, TPC6AΔ, involved in tau aggregation and Aβ generation, suggesting a protective role of WWOX protein in Alzheimer's Disease." (PMID 38161429, 2023).
Alzheimer disease (continued). "Apart from the “Total 17 NAbs” cluster, the NAb clusters for “Alzheimer’s disease” (SORL1, ADAM10, CLU and TREM2) and “Neurodegenerative disease” (SORL1, ADAM10, CLU and TREM2 and WWOX) showed the best diagnostic performance for AD with sensitivity (against 95% specificity) up to 0.759." (PMID 36922858, 2023). "Tumor suppressor WWOX inhibits cancer growth and retards Alzheimer’s disease (AD) progression." (PMID 35883580, 2022). "It is, however, crucial to understand that WWOX has been associated with many other disorders such as autism-spectrum disorders (ASD), Alzheimer’s disease (AD), Parkinson’s disease (PD), and multiple sclerosis (MS), the models of which will be briefly reviewed." (PMID 34831305, 2021). "Furthermore, decreased WWOX protein levels have been observed in Alzheimer’s disease patients compared to age-matched healthy controls." (PMID 33916893, 2021). "Suppression of WWOX expression by small interfering RNA induces Tau hyperphosphorylation and formation of neurofibrillary tangles in neuroblastoma SK-N-SH cells, suggesting a crucial role of WWOX in inhibiting Tau phosphorylation in the degenerative neurons of Alzheimer’s disease." (PMID 32000863, 2020). "Although WWOX mutations found in SCAR12 or WOREE are very rare, possibly because of intrauteral lethality, changes in its expression are very common in pathological states like Alzheimer’s disease or GBM." (PMID 31543760, 2019). "There is an emerging role of WWOX in a number of neurological disorders including early-onset epilepsy, autism spectrum disorder (ASD), multiple sclerosis (MS), and Alzheimer’s disease." (PMID 33916893, 2021). "In the case of brain tissue, the ability of WWOX to bind and regulate glycogen synthase kinase 3β (GSK-3β) was proved to be important for Alzheimer’s disease, in which a frequent WWOX downregulation is found among patients." (PMID 34204789, 2021). "Interestingly, WWOX has been recently involved in several neurological disorders such as autism spectrum disorder (ASD), multiple sclerosis (MS), and Alzheimer's Disease." (PMID 38161429, 2023). "WWOX is involved in binding and regulating GSK-3β activity, and this limits Tau hyperphosphorylation, neurite outgrowth in neuronal differentiation, and formation of neurofibrillary tangles (NFTs) and senile plaques in Alzheimer's disease (AD)." (PMID 25537520, 2014).
osteosarcoma (23 papers, 2013 to 2026). A usually aggressive malignant bone-forming mesenchymal neoplasm, predominantly affecting adolescents and young adults. "Experimental data from osteoblast and osteosarcoma models have shown that loss or inactivation of WWOX leads to aberrant RUNX2 activity, contributing to oncogenic processes through deregulated osteogenic signaling." (PMID 41141138, 2025). "It was also found that high WWOX expression was associated with reduced RUNX2 expression in osteosarcoma cell lines." (PMID 36271927, 2022). "Although no significant decrease in proliferation was observed for the variant with only WWOX overexpression (yet with consequent trend), the literature data indicate that WWOX inhibits proliferation of glioblastoma, osteosarcoma and cervical cancer." (PMID 33718178, 2021). "WWOX loss has been associated with human osteosarcoma and some animal models provide support for murine osteosarcoma development." (PMID 30370248, 2018). "We further found that methylation of WWOX gene promoter CpG island in the osteosarcoma of patients is associated with suppression of WWOX expression." (PMID 28977834, 2017). "Administration of DNA methylation inhibitors increased WWOX expression in MG-63 cells and methylation of WWOX gene promoter CpG island in the osteosarcoma of patients was associated with suppression of WWOX expression." (PMID 28977834, 2017). "Recent findings indicate the association of WWOX gene polymorphism with the risk of metastasis from osteosarcoma, that is known to metastasize in the brain and lungs." (PMID 28045433, 2017). "Ablation of WWOX in knock-out mouse strains (Wwox -/-) caused development of osteosarcomas, as well as osteopenia and bone growth retardation." (PMID 24098343, 2013). "This association may help explain our finding that WWOX expression in osteosarcoma tissues was a predictor of disease-free survival in osteosarcoma patients." (PMID 28977834, 2017). "In this study, we investigated whether and the underlying mechanisms by which WWOX affects angiogenesis and invasion in osteosarcoma." (PMID 28977834, 2017). "For example, loss of WWOX facilitates migration of ovarian cancer and osteosarcoma cells." (PMID 23459853, 2013). "Among these, WWOX and RUNX2 have been repeatedly implicated in other bone-related cancers such as osteosarcoma, making them logical candidates for investigation in ES." (PMID 41141138, 2025). "Our findings reveal BM mesenchymal stem cells as a platform to study osteosarcoma and Myc and its targets as WWOX effectors and early molecular events during osteosarcomagenesis." (PMID 38182577, 2024). "In a human osteosarcoma cell line model, the ectopic expression of WWOX inhibited proliferation and attenuated invasion in vitro and suppressed tumorigenicity in mice." (PMID 36271927, 2022). "Proliferation was found to be increased when WWOX gene was methylated in osteosarcoma, while apoptosis was potentiated in ovarian carcinoma through caspase-3 and PARP when WWOX was functional." (PMID 34204827, 2021). "The deletion of the WWOX gene is observed in 30% of osteosarcoma cases which likely is an initial event in osteosarcoma pathogenesis." (PMID 31798348, 2019). "In a previous study, periosteal osteosarcoma relapse occurred along the diaphysis in 31% of adolescent WWOX knockout mice." (PMID 28977834, 2017). "Overexpression of WWOX in osteosarcoma cells inhibited tube formation in co-cultured HUVEC cells, and high WWOX expression was associated with decreased MVD." (PMID 28977834, 2017). "WWOX overexpression in the osteosarcoma cells decreased, while WWOX knockdown in the osteosarcoma cells increased, tube formation in the HUVEC cells compared to the normal and negative controls." (PMID 28977834, 2017).
osteosarcoma (continued). "In this study, we investigated the role of WWOX in angiogenesis in human osteosarcoma and its effects on the expression of CD34, RUNX2, and VEGF to understand their potential interaction in the development of osteosarcoma." (PMID 28977834, 2017). "Intriguingly, transiently elevated expression of the lncRNA PARTICLE was found to accompany diminished WWOX transcript levels and promoter activity within in vitro models of osteosarcoma." (PMID 29152092, 2017). "While other factors such as abnormal gene copy number, can also reduce WWOX expression, our data suggest that DNA methylation is likely a key contributor to reduced WWOX expression in osteosarcoma cells." (PMID 28977834, 2017). "We further performed a methylation status analysis of WWOX gene promoter CpG island in the osteosarcoma of patients and found that methylation of WWOX gene promoter CpG island in the osteosarcoma of patients was associated with suppression of WWOX expression." (PMID 28977834, 2017). "In this study, we showed for the first time that WWOX expression was negatively associated with MVD and confirmed that WWOX overexpression in osteosarcoma cells inhibited tube formation in co-cultured HUVEC cells." (PMID 28977834, 2017). "Breakage of the fragile site FRA16D disrupts the WWOX (WW Domain Containing Oxidoreductase) tumor suppressor gene in osteosarcoma." (PMID 29152092, 2017). "In this study, we also found that WWOX promoted apoptosis in osteosarcoma cells, which is consistent with the results of previous studies." (PMID 28977834, 2017). "Together, these results suggest that reduced WWOX expression in osteosarcoma cells inhibited apoptosis, promoted invasion, upregulated bcl-2, OPN, RUNX2, and VEGF expression, and increased microvessel density (MVD)." (PMID 28977834, 2017). "Overexpression of WWOX in osteosarcoma cells inhibited tube formation in co-cultured HUVEC cells, and high WWOX expression was associated with decreased microvessel density (MVD)." (PMID 28977834, 2017). "Overexpression of WWOX increased apoptosis in all osteosarcoma cells, while WWOX knockdown decreased apoptosis in MG-63 cells, compared to the normal and negative controls." (PMID 28977834, 2017). "This is consistent with the work of Del Mare and Aqeilan, which showed that WWOX-induced inhibition of invasion in osteosarcoma cells was mediated by RUNX2." (PMID 28977834, 2017). "The WW domain-containing oxidoreductase (WWOX) is frequently altered in human osteosarcoma." (PMID 38182577, 2024). "Likewise, in a clinical trial, other authors analyzed the effect of methylation in the WWOX gene on osteosarcoma cell proliferation." (PMID 38140282, 2023). "However, Aqeilan and al. found that WWOX activates HR in the osteosarcoma cells U2OS, by interacting with ATM and stimulating its kinase activity." (PMID 37248434, 2023). "Ectopic expression of WWOX in different osteosarcoma cell lines inhibits metastasis, and the expression of RUNX2 and its target genes such as VEGF (vascular endothelial growth factor gene) involved in angiogenesis and MMP13 (matrix metalloproteinase-13 gene) involved in invasion." (PMID 33946771, 2021). "Ectopic expression of WWOX in the osteosarcoma U2OS cells induces HR." (PMID 33946771, 2021). "Indeed, several reports have shown that WWOX deletion or altered expression is a frequent event in osteosarcoma." (PMID 30370248, 2018). "We further demonstrated that exosomal RNAs including Annexin2, Smad2, MTAP, CIP4, PEDF, WWOX, Cdc5L, P27, could also discriminate good and poor chemotherapeutic response for osteosarcoma treatment." (PMID 29100284, 2017). "Deletion of WWOX in mice has resulted in the spontaneous development of osteosarcoma (OS)." (PMID 29152092, 2017).